HGF (hepatocyte growth factor)
Diseases named in the same sentence as HGF in open-access papers (continued):
Sharing a sentence is not in itself a finding about the gene and the disease.
cancer (continued). "When gingival-derived carcinoma Ca9-22 and gingival fibroblast HGF were used as target cells, TSM values of 77.8 and 31.2 were given, respectively." (PMID 37505064, 2023). "Different preclinical studies have shown that the inhibition of HGF activity is required to overcome therapeutic resistance in amplified cancer cells, thus increasing cancer patients’ overall survival." (PMID 35884597, 2022). "Several studies suggest that MET, together with its ligand HGF, promotes cancer cell hallmarks including cell proliferation, survival, migration, angiogenesis in multiple mammalian cancer including hepatocellular carcinoma, head and neck cancer etc.." (PMID 35432450, 2022). "Hepatocyte growth factor (HGF) is a multifunctional cytokine involved in embryogenesis, organogenesis, wound healing, and tissue repair and is also involved in tumorigenesis and cancer invasion." (PMID 36232862, 2022). "Hepatocyte growth factor (HGF)/ MET signaling is known to be able to initiate the epithelial-mesenchymal transition (EMT), of which the association with cancer stem cell (CSC) generation has been established." (PMID 34974522, 2022). "MET alterations, including amplification, mutations, gene fusion, MET/HGF protein over expression and the crosstalk between dysregulated MET and other signaling pathways, are associated with poor prognosis in cancers, and thus, molecularly targeted." (PMID 36551608, 2022). "The HGF/c-MET pathway is essential in regulating multiple processes involved in tumorigenesis and multiple pathways associated with cancer and is a promising therapeutic target." (PMID 36482562, 2022). "For these reasons, the HGF/c-MET axis pathway is seen as a prospective target in various cancers and many small molecules and therapeutic monoclonal antibodies are being evaluated in preclinical and clinical trials." (PMID 35630066, 2022). "In hepatocellular carcinoma, one of the synthetic analogs of chrysin named 8-bromo-7-methoxychrysin suppressed the activation of hepatic stellate cells to CAFs and decreased the level of stemness of cancer cells by modifying IL-6 and HGF signaling." (PMID 35327514, 2022). "c-Met is a tyrosine kinase receptor, a proto-oncogene expressed in both cancer and normal cells, activated by its ligand, the hepatocyte growth factor (HGF)." (PMID 39086964, 2022). "HGF-induced integrin clustering promotes cancer cell motility and invasion by activating actin-rich adhesion sites and lamellipodia." (PMID 35630066, 2022). "Aberrant MET/HGF signaling promotes mitogenesis, invasion and angiogenesis, thus contributing towards tumorigenesis and progression of cancer." (PMID 36551608, 2022). "Results from our scRNA-seq analyses identified several potential interactions involving the cancer stem cell marker CD44 with ligands secreted by CAFs such as HGF, HBEGF, FGF2 and LGALS9." (PMID 36273171, 2022). "HGF released by cancer and stromal cells impacts the development of cancer cells, promotes cancer cell proliferation and survival and stimulates metastatic dissemination via activating the signaling pathway of its receptor, c-MET." (PMID 35630066, 2022). "Oncogenesis driven by the signaling of HGF-induced MET/PI3K/AKT/c-MYC has been well-characterized in many different cancer types." (PMID 35941699, 2022). "The identification of the cancer cell-derived factors triggering HGF production by fibroblasts deserves further attention." (PMID 36010567, 2022). "In support of the link between cancer stemness and metastasis, our data show that the 2 stem cell regulators, activin and HGF, can promote CRC invasion and liver metastasis." (PMID 36591565, 2022). "Activating the HGF/c-Met signaling pathway also enhanced the migration and invasion ability of cancer cells to facilitate cancer cells invading nerves." (PMID 35449152, 2022). "MET-dependent signal transduction in cancer is activated by increased HGF and endows sustained resistance to TKIs." (PMID 36505831, 2022).
cancer (continued). "HGF is a multi-functional factor involved in cell growth, cell motility, and morphogenesis, and has been reported to be involved in cancer by promoting angiogenesis, tissue regeneration, tumourigenesis and metastasis." (PMID 36007304, 2022). "Thayaparan and his team have engineered T-cells to express HGF as a chimeric antigen receptor to target c-MET expressing cancer cells." (PMID 35081970, 2022). "For example, HGF/SF (Hepatocyte Growth Factor/Scatter Factor) favors both cancer cell and endothelial cell invasion." (PMID 36230504, 2022). "c-MET, a receptor for hepatocyte growth factor, has been reported to promote tumorigenicity in a variety of cancers." (PMID 36326232, 2022). "Cytoskeletal remodeling and reorganization are known to cause the major processes of cancer movement and metastasis, and the HGF/c-MET signaling route plays a critical role in cancer metastasis." (PMID 35630066, 2022). "In breast MDA-MB-231 cancer cells, a whole blueberry extract from Vaccinium angustifolium (30 μL/mL) hindered hepatocyte growth factor (HGF)-induced migration; this cellular outcome was associated with reduced p-AKT levels." (PMID 36355554, 2022). "Generation of inhibitory DNA aptamers against human HGF would be useful as therapeutic agents for cancers." (PMID 35551547, 2022). "Multiple reports have demonstrated that HGF/c-Met signaling cascades modulate the EMT process in various types of cancers." (PMID 36291760, 2022). "Targeting the HGF/MET signaling pathway has been a viable therapeutic strategy for various cancer types due to hyperactivation of HGF/MET axis occurs frequently that leads to detrimental cancer progression and recurrence." (PMID 35941699, 2022). "Activation of the HGF pathway can lead to increased cell survival, proliferation, and the metastatic spreading of cancer cells." (PMID 35884597, 2022). "In the case of c-Met in BC, it has been suggested that HGF/MET signalling is a mediator of resistance to anti-cancer immunotherapy, following the rationale of using anti-MET drugs in combination with immunomodulatory agents." (PMID 36498560, 2022). "Aberrant HGF/MET pathway plays as an oncogenic driver, since dysregulation of c-MET and HGF has been implicated in cancer pathogenesis as it is involved in the mechanisms of cell proliferation and survival, invasion, and metastasis." (PMID 35069735, 2022). "HGF/c-Met signaling promoted metastasis of cancer cells by regulating a diverse downstream prometastatic effector molecules, via Ras-MAPK/ERK, PI3K/AKT signaling, JAK2/STAT3 signaling." (PMID 35246503, 2022). "Accordingly, inhibition of the HGF/c-Met signaling pathway has been considered an effective approach for cancer therapy." (PMID 36499211, 2022). "The assay indicated that HGF significantly increased the number of cancer cells passing through the Matrigel-coated membrane." (PMID 36139568, 2022). "Remarkably, we identified a positive correlation between myoferlin expression and both c-Met and HGF expression in cancer cells, which corroborates a strong connection between myoferlin and the HGF/c-Met pathway in ccRCC." (PMID 35205843, 2022). "Several TKIs or anti-cancer drugs, including cabozantinib and gefitinib, can inhibit HGF/c-MET-, ANG-2/Tie-2-, and/or EGF/EGFR-mediated signaling." (PMID 35008398, 2022). "Further mechanistic studies indicated that the hepatocyte growth factor (HGF)/c-Met pathway was activated in cancer stem cell enrichment." (PMID 36698408, 2022). "Impacts of miR-144-3p and HGF on cancer cellular proliferation, migration and invasion were elucidated by CCK-8, Flow cytometry, Transwell invasion and Wound-healing assay." (PMID 35568918, 2022). "Activating the HGF/c-Met signaling pathway increased the cancer cell invasion index and DRG outgrowth index." (PMID 35449152, 2022).
cancer (continued). "A recent study found that Tankyrase2, a poly-ribose polymerase involved in wnt signaling, facilitated HGF-induced microtubule assembly in the cancer cells and inhibited of Tankyase 2 lung cancer cell invasion and migration." (PMID 35630066, 2022). "Persistent activation of HGF-induced phenotypes contributes to the progression of invasion and metastasis, as well as the growth and survival of cancer cells." (PMID 35085554, 2022). "Further, the serine protease urokinase plasminogen activator (uPA, encoded by PLAU) activates pro-HGF (secreted by pancreatic stellate cells) to active HGF, which binds to the c-MET receptor on cancer cells, activating several downstream signalling molecules." (PMID 36591282, 2022). "Hyperactivation of HGF/MET signaling is shown to initiate epithelial–mesenchymal transition (EMT) phenomenon to promote metastasis via enriching cancer stem cells (CSCs) that contribute to chemoresistance." (PMID 35941699, 2022). "Compared to the normal control group, Panc02 cancer cells treated with HGF enhanced cell viability in the presence of ferroptosis inducers." (PMID 35693705, 2022). "Dysregulated expression of HGF/c-MET acts as a catalyst in many cancers, with overexpression of HGF often leading to aberrant cell proliferation and extracellular matrix invasion." (PMID 35778602, 2022). "Targeting the HGF/MET pathway is a promising strategy because it is involved in different cancer types." (PMID 35626056, 2022). "The increased uPA level further activates pro-HGF, resulting in a feed-forward activation loop to promote cancer progression." (PMID 36591282, 2022). "Here, we report for the first time using an in silico approach, that Galangin is able to inhibit the HGF/c-Met axis in CCA, which is implicated for its oncogenic role in several cancer types, including CCA." (PMID 35889537, 2022). "HGF secretion by CAFs is supported by lactate hypersecretion by cancer cells, which demonstrates a real dialog between CAFs and cancer cells." (PMID 35681591, 2022). "In lung carcinoma, EGFR- or MET-expressing cancer cells exhibited an elevated glycolysis activity and increased production of lactate that induced CAFs to secrete large amounts of HGF through an NF-κB-dependent mechanism." (PMID 35814444, 2022). "For example, CAF-derived HGF increases the resistance of CD73+ cancer cells to sorafenib or cisplatin through the HGF-c-Met-ERK1/2 pathway in HCC." (PMID 36457492, 2022). "In the same way, scratched gaps of carcinoma cells closed 1.6 times faster than the control group within 96 h when treated with both hGF-CM or mixed-culture CM." (PMID 36359794, 2022). "Generally, MET is thought to play a central role in signaling pathways to control cell proliferation, survival, and migration, in response to binding by its ligand HGF during developmental morphogenesis and in multiple cancer types." (PMID 34202288, 2021). "Among the RTKs, the HGF/MET axis frequently has been reported to be responsible for resistance to inhibition of other RTKs in various types of cancer and in GBM." (PMID 34806012, 2021). "Remarkably, emerging evidence has shown that the HGF/c-Met signaling pathway activation promoted cancer cell migration and invasiveness." (PMID 34456716, 2021). "Two different relationships between chemoresistance and MET activated on endothelial cells through cancer cell-derived HGF have been shown." (PMID 33526881, 2021). "T cells were showed to express c-Met, which was reportedly involved in immune system activation against cancer cells overexpressing HGF." (PMID 34413852, 2021). "WNT4, HGF and TGFB1 are associated with the molecular signaling pathways in cancer, proteoglycans in cancer, and the relaxin signaling pathway." (PMID 33959508, 2021). "HGF, which is well known for its correlation to cancer aggressiveness and poor prognosis, is commonly overexpressed in solid tumors and acts as a single ligand for the MET proto-oncogene, receptor tyrosine kinase (c-Met) surface receptor." (PMID 34514097, 2021).
cancer (continued). "c-MET receptor and its ligand, the hepatocyte growth factor (HGF) is known to play an important role in cancer growth and metastasis as well as development of drug resistance, especially with VEGFR inhibitors." (PMID 34563169, 2021). "Nowadays, HGF/c-Met signaling has been recognized as a promising cancer therapeutic target, and many types of inhibitors have been developed to eliminate the activation of this pathway." (PMID 34970484, 2021). "One of the important signalling pathways that mediates cancer cell–PSC interactions is the hepatocyte growth factor (HGF)/c-Met pathway." (PMID 34199452, 2021). "In hepatocellular carcinoma, HGF sustained cancer cell stemness through the activation of MET/FRA1/HEY1 cascade." (PMID 34354950, 2021). "Met suppression using Met inhibitors or Met activation using hepatocyte growth factor (HGF) upregulated or downregulated PD-L1 expression in different human cancer cell lines, respectively." (PMID 34088360, 2021). "Since CAFs secrete higher levels of HGF than normal stromal cells, the CAFs were postulated as the culprits driving cancer cell migration." (PMID 33535458, 2021). "SNHG3 was previously found to exert oncogenic roles in a plethora of cancers: Based on current studies, SNHG3 was involved in TGF-β, NOTCH, JAK2/STAT3 and HGF pathway to promote cancer cell proliferation, invasion and inhibit apoptosis rate." (PMID 33596916, 2021). "These two protease inhibitors have been reported to be aberrantly expressed in many types of cancer and represent one of the mechanisms of HGF/MET signaling." (PMID 34381422, 2021). "CAF, as a part of the surrounding matrix in TME, can increase the stem cell-like characteristics of cancer cells by secreting growth factors such as HGF, thus regulating the differentiation of cancer stem cells." (PMID 35096588, 2021). "Breast cancer cell motility towards HUVEC conditioned medium is impaired by cancer cell c-Met knockdown or by HUVECs HGF knockdown." (PMID 33783686, 2021). "These two studies indicate that MET activation on endothelial cells by HGF secreted by cancer cells can facilitate chemoresistance in two different ways." (PMID 33526881, 2021). "Taken together, our findings suggest that the HGF/c-Met pathway is involved in Treg accumulation in the context of cancer." (PMID 34771724, 2021). "Over the past few years, different strategies have been pursued to develop HGF/c-Met targeted therapies for management of different types of cancer." (PMID 33574356, 2021). "Exploiting a co-culture system of human pancreatic stellate cells and cancer cells, we demonstrated that fibroblast activation was reduced upon HGF/MET axis inhibition." (PMID 34298732, 2021). "Hepatocyte growth factor (HGF) signaling plays a plethora of roles in tumorigenesis and progression in many cancer types." (PMID 34381422, 2021). "In a cancer context, HGF/c-MET activation exerts pro-angiogenic effects, leading to a direct activation of ECs and an indirect stimulation of other pro-angiogenic factors, as VEGF." (PMID 33916438, 2021). "The migration of cancer cells toward blood vessels is also stimulated both in vitro and in vivo with EC-derived HGF which promotes cancer cell migration in a c-Met receptor–dependent manner." (PMID 33783686, 2021). "We found that HGF enhanced the adipocyte-cancer cell interactions as a downstream effector of adipsin." (PMID 34439392, 2021). "An additional example is the activation of c‐MET receptors by HGF, which results in enhanced production by cancer cells of MMP1, MMP2, and MMP9, enzymes that can degrade extracellular matrix proteins." (PMID 34542930, 2021).
cancer (continued). "The contacts between activated Met kinase and mitochondria formed dramatically, and an intact HGF/Met axis was necessary for dysregulated mitochondrial fission and cancer cell movements." (PMID 34848680, 2021). "This opposes nuclear import of G-actin leading to depletion of nuclear G-actin, which, in turn, activates the MRTF/SRF transcription factor to enable HGF-driven scattering and invasive behaviour of cancer cells." (PMID 34819513, 2021). "Hepatocyte growth factor (HGF), another important molecules secreted by CAFs, promotes cancer cell invasiveness." (PMID 34354950, 2021). "In this work, we found that HGF, a protumoral and proangiogenic factor, is involved in Treg increase in the peripheral blood of cancer patients." (PMID 34771724, 2021). "HGF, secreted by CAFs, plays a crucial role in invasion, proliferation and metastasis of cancer cells." (PMID 33673405, 2021). "Simultaneously, an increased expression level of E-cadherin was observed after treatment with HGF+D. kaki leaf extract, suggesting D. kaki has the ability to inhibit cancer cell growth despite addition of HGF to the cells." (PMID 34830907, 2021). "In particular, HGF produced by hepatic stellate cells and stromal cells is known to induce resistance to cancer therapy." (PMID 34771620, 2021). "HGF facilitates transformed epithelial cell migration and protects cancer cells from chemotherapeutic agents." (PMID 34073987, 2021). "c-Met and HGF are dysregulated in cancer cells, and they are believed to contribute to tumor invasion, making the pathway an attractive candidate for targeted cancer therapy." (PMID 33750878, 2021). "In the microenvironment of HCC, HGF plays a pivotal role in the migration and invasion of cancer cells through activation of Met kinase acting on mitochondrial fission directly." (PMID 34848680, 2021). "Many explanations exist for this contradictory phenomenon, such as the interaction between TIMP1 and CD63 to activate MAPK signalling and participation in the HGF/c-Met pathway to promote cancer progression." (PMID 34781885, 2021). "In various cancer types, hepatocyte growth factor (HGF) and c-Met, its receptor, have been explained to be implicated in the EMT program." (PMID 34456716, 2021). "Mechanistically, the CAF-derived HGF interacts with c-Met receptors on cancer cells to activate numerous signaling pathways, especially those related to EMT and metastasis." (PMID 33535458, 2021). "HGF/c-Met signaling is drawing attention as an important target molecule for anticancer therapy because it is related to cancer cell generation, growth, invasion, and metastasis, and various small molecule and antibody therapeutics are being developed." (PMID 34683124, 2021). "HGF promotes cancer stemness and increases the clonogenicity, whereas IL-6 mainly contributes to enhance the invasion of CMS2 CR-CSphCs." (PMID 34408135, 2021). "Ephedrine has been described to suppress hepatocyte growth factor (HGF)-induced cancer cell motility by preventing both HGF-induced phosphorylation of c-Met and its tyrosine kinase activity." (PMID 33809976, 2021). "HGF, a scattering factor, influences cancer cell proliferation, survival, invasion, and metastasis through interaction with c-MET." (PMID 33466394, 2021). "The hybrid molecules correctly bind MET and HGF, inhibit HGF-induced MET downstream signaling, and quench HGF-driven biological responses, such as growth, motility and invasion, in cancer cells of different origin." (PMID 33446252, 2021). "c-MET, a kinase receptor for Hepatocyte growth factor (HGF), drives tumorigenesis repressing the Raf kinase inhibitory protein (RKIP), whose loss has been reported in many cancer types overexpressing c-MET, including 50% of CRC." (PMID 34768901, 2021). "Alternatively, HGF secretion by cancer cells can trigger chemoresistance through altering angiogenesis and triggering hypoxia." (PMID 33526881, 2021).